TRPC4 (transient receptor potential cation channel subfamily C member 4)
Description:
Forms a receptor-activated non-selective calcium permeant cation channel. Acts as a cell-cell contact-dependent endothelial calcium entry channel. Forms a homomeric ion channel or a heteromeric ion channel with TRPC1; the heteromeric ion channel has reduced calcium permeability compared to the homomeric channel. Also permeable to monovalent ions including sodium, lithium and cesium ions. [Isoform Beta]: Forms a receptor-activated non-selective calcium permeant cation channel.
Synonyms: hTrp-4; hTrp4; TRP4
Tractability: Small molecule: a structure with a bound ligand is known; a high-quality ligand is known; it belongs to a druggable protein family. Antibody: UniProt places it where antibodies can reach, with high confidence; its Gene Ontology location is reachable by antibodies, with high confidence; UniProt predicts a signal peptide or a membrane-spanning region. PROTAC: its protein half-life has been measured; a small molecule that binds it is known.
Target class: Voltage-gated ion channel; Ion channel; Transient receptor potential channel
Chemical probes: Englerin-A, ML204
Gene: Protein-coding gene on chromosome 13 (37,632,063 to 37,870,204, reverse strand). Ensembl gene ENSG00000133107.
Subcellular location: Cell membrane; Cell membrane (Isoform Beta)
Pathways (Reactome):
Developmental Biology: Role of second messengers in netrin-1 signaling
Transport of small molecules: TRP channels
Gene Ontology:
Molecular function: beta-catenin binding; cadherin binding; calcium channel activity; monoatomic cation channel activity; protein binding; store-operated calcium channel activity; inositol 1,4,5 trisphosphate binding; monoatomic ion channel activity
Biological process: calcium ion import; calcium ion transmembrane transport; calcium ion transport; membrane depolarization; regulation of cytosolic calcium ion concentration; monoatomic ion transport; regulation of membrane depolarization; transmembrane transport
Cellular component: basolateral plasma membrane; calcium channel complex; cation channel complex; cell surface; cell-cell junction; cortical cytoskeleton; plasma membrane; caveola; membrane; membrane raft; protein-containing complex
Genetic constraint (gnomAD): Loss-of-function variants: 48 observed, 100.01 expected, observed/expected ratio (o/e) 0.48, 90% interval 0.38 to 0.61. The upper end of that interval is the gene's LOEUF score, 0.61, which puts it in group 2 of 6, group 1 being the genes least tolerant of losing a copy. Missense variants: 897 observed, 1,195.5 expected, observed/expected ratio (o/e) 0.75, 90% interval 0.71 to 0.79. Synonymous variants: 453 observed, 443.59 expected, observed/expected ratio (o/e) 1.02, 90% interval 0.94 to 1.1.
Homologues: Orthologues: chimpanzee TRPC4 (100% identical), macaque TRPC4 (99% identical), rabbit TRPC4 (99% identical), dog TRPC4 (98% identical), pig TRPC4 (97% identical), guinea pig TRPC4 (97% identical), rat Trpc4 (97% identical), mouse Trpc4 (97% identical), tropical clawed frog trpc4 (79% identical), zebrafish trpc4b (71% identical), zebrafish trpc4a (68% identical), Drosophila melanogaster Trpgamma (44% identical), and 3 more. Paralogues in human: TRPC5 (64% identical), TRPC1 (38% identical), TRPC7 (33% identical), TRPC6 (33% identical), TRPC3 (32% identical).
Diseases named in the same sentence as TRPC4 in open-access papers:
TRPC4 is named in the same sentence as 95 diseases in open-access papers, as found by Europe PMC text mining. Sharing a sentence is not in itself a finding about the gene and the disease. The quoted sentences say what the papers report.
Anxiety (15 papers, 2013 to 2026). Intense feelings of nervousness, tension, or panic often arise in response to interpersonal stresses. "TRPC5 is highly homologous to TRPC4, and both are involved in the neurobiological mechanisms underlying the regulation of anxiety and depression." (PMID 41584354, 2026). "TRPC4 was found to be abundant in the corticolimbic regions of the brain and was implicated in fear and anxiety-like behaviors." (PMID 39611176, 2024). "Continuing the mechanisms of anxiety, TRPC4 and TRPC5 are heavily implicated in the transmission of conditioned fear responses to the amygdala, and gene disruption in mice demonstrated anxiolytic effects." (PMID 36902145, 2023). "Since TRPC channels have been implicated in anxiety-like behaviors, we tested the antidepressant potential of the newly identified TRPC4/C5 inhibitor, M084, on mice." (PMID 26317356, 2015). "In addition, this study showed that TRPC4 protein knockdown limited to the lateral amygdala region—a region of the brain implicated in anxiety—showed the same phenotype as global Trpc4−/− mice." (PMID 29865154, 2018). "A similar study in TRPC4−/− mice demonstrated diminished anxiety or innate fear relative to wild-type mice." (PMID 38903645, 2024). "In contrast, TRPC4 inhibitors, such as HC-070 and M084, have been reported to significantly alleviate depressive and anxiety-related behaviors." (PMID 39611176, 2024). "A range of studies have systematically explored the association between TRPC4 and CNS disorders, for example, the activation of TRPC4 led to anxiety, fear-related responses, and major depressive disorder (Nazıroğlu and Demirdaş, 2015)." (PMID 39611176, 2024). "We also report on clinical studies of BI 1358894, a small molecule inhibitor of TRPC4/5 ion channels, demonstrating reduced psychological and physiological responses to induced anxiety/panic-like symptoms in healthy volunteers." (PMID 39343822, 2024). "TRPC4 was identified by the same group of researchers to be essential for behavioral responses to anxiety-inducing stimuli, seeing as KO mice demonstrated an anxiolytic behavioral phenotype." (PMID 36902145, 2023). "Trpc4 KO mice also showed suppressed Gα q/11-dependent responses in the amygdala, which regulate fear-related behavioral processes, and decreased anxiety-like behaviors (see “Neuronal and Glial Functions of Redox-Sensitive TRP Channels” section)." (PMID 33644051, 2021). "This proposed role of TRPC4/5 channels in fear behaviour has led to TRPC1/4/5 modulators being investigated as a possible treatment for anxiety." (PMID 29865154, 2018). "Because there are features of anxiety in this model, we probed the effect of inhibiting TRPC4 and TRPC5." (PMID 29385160, 2018). "Our results provide strong evidence that acute inhibition of TRPC4 and TRPC5 with HC-070 reduces behavior associated with anxiety and depression in mouse models." (PMID 29385160, 2018). "Our findings are in good agreement with the recent studies, which reported that gene ablation of either TRPC4 or TRPC5 decreased anxiety-like behaviors in mice." (PMID 26317356, 2015). "Here, we show that intraperitoneal injection of this novel TRPC4/C5 inhibitor produced anti-depressive and anti-anxiety effects in mice, further supporting its utility in pharmaceutical research." (PMID 26317356, 2015). "Trpc4 knockout rats exhibit a phenotype of reduced social exploration and heightened social anxiety." (PMID 23717492, 2013). "The TRPC4/C5 antagonist, BI-1358894 (Boehringer Ingelheim, Ingelheim am Rhein, Germany), was well-tolerated in human volunteers and reduced the severity of experimental panic attack." (PMID 41516061, 2025). "Trpc4 (location of cis-eQTL: Chromosome3 54.266176 Mb) may be involved in the regulation of anxiety-related behaviours." (PMID 35456420, 2022). "Genetic deletion of either TRPC4 or TRPC5 reduces anxiety behaviors in mice." (PMID 29385160, 2018).
Anxiety (continued). "Interestingly, these anxiolytic-like behaviors in TRPC4−/− mice were only present in stressful test conditions (bright versus dim lighting) suggesting the TRPC4 effects are more readily revealed in anxiety-provoking situations, a desirable effect in the treatment of PTSD." (PMID 38903645, 2024). "Taken together, these data support the hypothesis that TRPC4/C5 represent novel and safe non-opioid targets for the treatment of several pain conditions, in addition to attenuating suffering, depression, and anxiety associated with chronic pain." (PMID 36834762, 2023). "There is earlier evidence that the amygdala, highly expressing TRPC4 and TRPC5, is essential in fear, anxiety, and depression." (PMID 36834762, 2023). "TRPC4 and TRPC5 are highly expressed in the cortex and amygdala, the regions thought to be crucial in regulating anxiety." (PMID 33644051, 2021). "Both TRPC4 and TRPC5 have been shown to be involved in anxiety-like behavior in the mouse model of fear conditioning test." (PMID 26317356, 2015). "TRPC4/C5 is thought to regulate negative pain-related emotions, such as fear and anxiety, in the brain." (PMID 41516061, 2025). "In the behaving mouse, inhibition of TRPC4 and TRPC5 results in anxiolytic disinhibition of exploration in a CCK-anxiety model, decreased marble burying, increased activity in tests of antidepressant efficacy, and amelioration of hyper-fear memory in socially stressed mice." (PMID 29385160, 2018). "Taken together, these data suggest that TRPC4 and TRPC5 channels may be important targets for the treatment of anxiety and depression." (PMID 29385160, 2018). "We provide preclinical evidence that the lack of TRPC4 and TRPC5 channels or its pharmacological inhibition attenuate fear and anxiety without impairing other behaviors in mice." (PMID 39343822, 2024).
cardiac hypertrophy (9 papers, 2016 to 2024). "TRPC4 is also associated with several cardiovascular diseases, including cardiac hypertrophy, heart failure, and hypertension." (PMID 39108834, 2024). "For example, heart conditions including hypertension and cardiac hypertrophy have been linked to abnormal TRPC4 expression." (PMID 38025430, 2023). "Suppression of TRPC4 activity by expression of a dominant-negative mutant of TRPC4 suppressed transverse aortic constriction induced cardiac hypertrophy." (PMID 32079284, 2020). "In our study, gene expression of TRPC4 channel was significantly decreased, which is controversial, because transgenic mice overexpressing dominant negative TRPC4 mouse showed significantly reduced cardiac hypertrophy after transverse aortic constriction." (PMID 31315301, 2019). "Another recent study suggests a combined activity of TRPC4 with TRPC1 causing a background Ca2+ entry, which causes an elevation of diastolic and systolic Ca2+ levels and induces reactive signaling and cardiac hypertrophy." (PMID 27992507, 2016). "The Transient Receptor Potential Channel Subunit 4 (TRPC4) has been considered as a crucial Ca2+ component in cardiomyocytes promoting structural and functional remodeling in the course of pathological cardiac hypertrophy." (PMID 27992507, 2016). "The current study showed a reduced expression of Rcan1 and enhanced cardiac remodeling in the absence of Orai, whereas reduced Rcan1 expression in the absence of TRPC1/TRPC4 led to a decrease in the development of cardiac hypertrophy." (PMID 32354146, 2020).
epilepsy (6 papers, 2018 to 2025). A brain disorder characterized by episodes of abnormally increased neuronal discharge resulting in transient episodes of sensory or motor neurological dysfunction, or psychic dysfunction. "Though the relationship between TRPC4 and visceral hypersensitivity remains unclear, recent studies have implicated its hyperexcitability in the neurons of patients with epilepsy." (PMID 40244137, 2025). "Thus, the downregulation of TRPC4 channel function may be an effective strategy for treating seizure disorders associated with ZIKV infection." (PMID 39009885, 2024). "Furthermore, TRPC4 channels in neurons influence synaptic transmission, and dysfunction in these channels may be associated with neurological conditions such as epilepsy." (PMID 38025430, 2023). "As first reported in 1995, TRPC1 protein can interact with TRPC4 and TRPC5 to form TRPC1/4/5 channels, which are significantly implicated in epilepsy." (PMID 34697589, 2021). "TRPC4 and TRPC5 channels are expressed in the central nervous system where their activation has been associated with epilepsy and fear." (PMID 30038709, 2018). "Moreover, in pilocarpine-induced epilepsy, TRPC4/TRPC5 blockade significantly inhibits seizure severity." (PMID 34489621, 2021).
depression (5 papers, 2015 to 2026). "Thus, together with the literature data, our results suggest a novel pathway involving CCK receptors and TRPC4/C5 channels in depression/anxiety disorders." (PMID 26317356, 2015). "Although the possibility could not be ruled out that the effect of M084 was induced by targets other than TRPC4/5, such as other depression/anxiety-related receptors and transporters, our results propose M084 as a lead compound for further druggability research." (PMID 26317356, 2015).
lung carcinoma (5 papers, 2013 to 2021). "Two intronic SNPs of TRPC4 (rs9547991 and rs978156) and one intronic SNP of TRPC7 (rs11748198) were consistently found to be associated with lung cancer in Chinese patients." (PMID 31936014, 2020). "Using isoform-specific blocking antibodies, we found that the blockade of TRPC1, TRPC4 and TRPC6 channels causes a significant inhibition of A549 cell proliferation, suggesting that TRPC1, TRPC4 and TRPC6 are important for lung cancer cell proliferation." (PMID 23840757, 2013). "In this study, we have shown that TRPC1, TRPC3, TRPC4 and TRPC6 exist in human lung cancer including the adenocarcinoma, squamous cell carcinoma and the adenocarcinoma-derived cell line A549." (PMID 23840757, 2013). "On the contrary, over-expression of TRPC1 and TRPC6 increased the A549 proliferation, however the effect of overexpression of TRPC3 and TRPC4 has not achieved significance in the lung cancer cells." (PMID 23840757, 2013). "Linear multivariance regression analysis also showed a negative correlation of the mRNA expression of TRPC1, TRPC3, TRPC4 and TRPC6 to lung cancer differentiation grade with standardized β coefficient sequence of TRPC1 (−0.563)>TRPC4 (−0.360) >TRPC6 (+0.271) and TRPC3 (−0.057), respectively." (PMID 23840757, 2013). "In conclusion, we found that TRPC1, TRPC3, TRPC4 and TRPC6 channels are expressed in lung cancer." (PMID 23840757, 2013).
autism (4 papers, 2022 to 2025). Persistent deficits in social interaction and communication and interaction as well as a markedly restricted repertoire of activity and interest as well as repetitive patterns of behavior. "Variations in the genes TMPRSS4, TRPC4, and PCDH9 were consistently linked to autism across the two independent samples, highlighting the role of calcium signaling and cell adhesion molecules in the risk of autism-related disorders." (PMID 39766876, 2024). "Two novel autism genes, TRPC4 and SCFD2, were discovered in two Qatari autism individuals." (PMID 38025430, 2023). "They play an important role in dopamine-related processes, including addiction and attention (TRPC4), physiological and pathological processes in the central nervous system (GRIN3A), autism (NBEA), etc." (PMID 35205240, 2022).
endothelial dysfunction (4 papers, 2018 to 2026). In vascular diseases, endothelial dysfunction is a systemic pathological state of the endothelium (the inner lining of blood vessels) and can be broadly defined as an imbalance between vasodilating and vasoconstricting substances produced by (or acting on) the endothelium. "Using Trpc4-KO rats, Francis and collaborators demonstrated that TRPC4 provides a Ca2+ source associated with endothelial dysfunction in the pathophysiology of PAH." (PMID 30322215, 2018). "Furthermore, TRPC4 appears to be associated with endothelial permeability in PAH; TRPC4 has been shown to increase the frequency of endothelial Ca2+ transients in severe PAH, functioning as a source of Ca2+ associated with endothelial dysfunction and the pathophysiology of PAH." (PMID 35454073, 2022). "In our hands, inhibition of PC1-mediated TRPC4β activity induced endothelial dysfunction, as demonstrated by the reduction of endothelial migration and cell-cell junctions by down-regulation of PC1 or TRPC4." (PMID 29472562, 2018). "We hypothesize that TRPC1, TRPC3, TRPC4, and TRPC6 act as critical molecular effectors mediating hypoxia-driven calcium influx and downstream signaling pathways that lead to pulmonary vascular remodeling, endothelial dysfunction, and increased pulmonary arterial pressure." (PMID 41751997, 2026).
medulloblastoma (4 papers, 2017 to 2024). A malignant, invasive embryonal neoplasm arising from the cerebellum. "TRPC4 contributes to enhanced invasion and metastasis of granule precursor-derived human medulloblastoma." (PMID 29772843, 2018). "Here, the authors use OGR1 to induce the expression of TRPC4 which promotes the migration of medulloblastoma cells." (PMID 29772843, 2018). "TRPC4-activation by GPR68 agonists promoted the invasion and metastasis of granule precursor-derived human medulloblastoma." (PMID 36046118, 2021).
myocardial infarction (4 papers, 2016 to 2021). Gross necrosis of the myocardium, as a result of interruption of the blood supply to the area, as in coronary thrombosis. "A missense SNP (TRPC4-I957V) in the TRPC4 human gene was further found to be associated with a reduced risk of myocardial infarction." (PMID 29472562, 2018). "Interestingly, a missense SNP of TRPC4 (I957V) was found to reduce the risk of myocardial infarction (MI) in diabetic patients." (PMID 31936014, 2020). "Another study demonstrated that up-regulation of TRPC4 in the course of myocardial infarction (MI) could cause excessive sarcoplasmic reticulum (SR) Ca2+ loading and Ca2+ leakage which might contribute to a depressed contractile reserve during disease." (PMID 27992507, 2016).
psoriasis (4 papers, 2011 to 2023). An autoimmune condition characterized by red, well-delineated plaques with silvery scales that are usually on the extensor surfaces and scalp. "Using imiquimod-induced psoriasis model mice, they demonstrated that TRPC4 was expressed in a subset of peptidergic neurons expressing TRPV1 that innervate the skin." (PMID 33182442, 2020). "Although further studies are needed, specific TRPC4 inhibitors may be effective in the treatment of itch and inflammation in psoriasis." (PMID 33182442, 2020). "Because TG and CGRP are critical in migraine pathophysiology and considering our finding that TRPC4 is highly expressed in TG tissues and its inhibition reduced CGRP in a model of psoriasis, we asked if TRPC4 inhibition may offer a therapeutic option for the treatment of migraine." (PMID 34790097, 2021). "We have recently characterized the expression of TRPC4 in primary sensory neurons expressing CGRP and demonstrated a functional and therapeutic role of TRPC4 in primary sensory neurons in an animal model of psoriasis." (PMID 34790097, 2021). "Similarly, the stainings for TRPC4 and TRPC6 were also weaker in psoriasis lesions." (PMID 21364982, 2011).